RNU6-11P (RNA, U6 small nuclear 11, pseudogene)
Synonyms: RNU6-11
Gene: Small nuclear RNA gene on chromosome 7 (123,790,605 to 123,790,711, reverse strand). Ensembl gene ENSG00000201104.
Homologues: Orthologues: macaque U6 (100% identical), pig U6 (100% identical), rat U6 (100% identical), dog U6 (98% identical), rabbit U6 (98% identical). Paralogues in human: RNU6-37P (100% identical), RNU6-1 (98% identical), RNU6-2 (98% identical), RNU6-3P (98% identical), RNU6-4P (98% identical), RNU6-5P (98% identical), RNU6-6P (98% identical), RNU6-7 (98% identical), RNU6-8 (98% identical), RNU6-9 (98% identical), RNU6-12P (97% identical), RNU6-13P (97% identical), and 1289 more.